APOBEC3A (apolipoprotein B mRNA editing enzyme catalytic subunit 3A)
Description:
DNA deaminase (cytidine deaminase) with restriction activity against viruses, foreign DNA and mobility of retrotransposons. Exhibits antiviral activity against adeno-associated virus (AAV) and human T-cell leukemia virus type 1 (HTLV-1) and may inhibit the mobility of LTR and non-LTR retrotransposons. Selectively targets single-stranded DNA and can deaminate both methylcytosine and cytosine in foreign DNA. Can induce somatic hypermutation in the nuclear and mitochondrial DNA. May also play a role in the epigenetic regulation of gene expression through the process of active DNA demethylation.
Synonyms: A3A; ARP3; PHRBN; bK150C2.1
Tractability: Small molecule: it belongs to a druggable protein family. PROTAC: ubiquitination databases record sites on it; a small molecule that binds it is known.
Target class: Enzyme; Hydrolase
Gene: Protein-coding gene on chromosome 22 (38,952,741 to 38,963,184, forward strand). Ensembl gene ENSG00000128383.
Subcellular location: Nucleus; Cytoplasm
Subcellular location (Human Protein Atlas): Nucleoplasm
Pathways (Reactome):
Metabolism of RNA: Formation of the Editosome; mRNA Editing: C to U Conversion
Gene Ontology:
Molecular function: cytidine deaminase activity; protein binding; RNA binding; hydrolase activity; zinc ion binding
Biological process: clearance of foreign intracellular DNA; defense response to virus; innate immune response; negative regulation of viral genome replication; positive regulation of gene expression via chromosomal CpG island demethylation; transposable element silencing; cytidine to uridine editing; DNA cytosine deamination; negative regulation of single stranded viral RNA replication via double stranded DNA intermediate
Cellular component: cytoplasm; nucleus; P-body
Genetic constraint (gnomAD): Loss-of-function variants: 10 observed, 18.85 expected, observed/expected ratio (o/e) 0.53, 90% interval 0.33 to 0.9. The upper end of that interval is the gene's LOEUF score, 0.9, which puts it in group 3 of 6, group 1 being the genes least tolerant of losing a copy. Missense variants: 168 observed, 198.37 expected, observed/expected ratio (o/e) 0.85, 90% interval 0.75 to 0.96. Synonymous variants: 68 observed, 74.79 expected, observed/expected ratio (o/e) 0.91, 90% interval 0.75 to 1.11.
Homologues: Orthologues: macaque APOBEC3B (82% identical), macaque APOBEC3A (77% identical). Paralogues in human: APOBEC3B (87% identical), APOBEC3G (63% identical), APOBEC3D (40% identical), AICDA (39% identical), APOBEC3F (39% identical), APOBEC3C (36% identical), APOBEC3H (31% identical), APOBEC2 (29% identical), APOBEC1 (24% identical).
Diseases named in the same sentence as APOBEC3A in open-access papers:
APOBEC3A is named in the same sentence as 88 diseases in open-access papers, as found by Europe PMC text mining. Sharing a sentence is not in itself a finding about the gene and the disease. The quoted sentences say what the papers report.
breast cancer (39 papers, 2013 to 2026). A primary or metastatic malignant neoplasm involving the breast. "APOBEC-induced mutations occur in 50% of sequenced human tumors, with APOBEC3A (A3A) being a major contributor to mutagenesis in breast cancer cells." (PMID 38805570, 2024). "APOBEC3-associated mutations play an important role in the development of breast cancer and APOBEC3A was recently reported to be the main driver of these mutations." (PMID 38659038, 2024). "In breast cancer, a deletion polymorphism that generates an APOBEC3A/B chimera is associated with increased disease risk, more APOBEC3-induced mutations, and poor tumor differentiation (a sign of negative prognosis)." (PMID 36978147, 2023). "We aimed to evaluate the expression of APOBEC3A (A3A), 3B (A3B) mRNA, and germline APOBEC3A/B deletion polymorphism in patients with breast cancers and to investigate the correlation between their expressions and clinicopathological characteristics." (PMID 32176735, 2020). "We found that 77 (55.8%) patients carried a single-copy deletion of APOBEC3A/B, and A3B mRNA expression levels showed a tendency to be lower in breast cancers with A3B deletion allele." (PMID 32176735, 2020). "This deletion is more common in East Asians and case-control studies in Asian populations have found that the APOBEC3A/B deletion allele was associated with increased risk for breast cancer." (PMID 32176735, 2020). "Association of APOBEC3A/B deletion polymorphism with clinicopathological features in patients with breast cancers." (PMID 32176735, 2020). "We aimed to evaluate the expression of A3A and A3B mRNA according to subtypes and the incidence of APOBEC3A/B deletion polymorphisms in Korean patients with breast cancers." (PMID 32176735, 2020). "Consistent with the univariate analysis, a striking association for uc011aoc (APOBEC3A/B) with APOBEC-mutational signature was observed in breast cancer (P = 5.3 × 10− 11), and an additional association was also observed in lung adenocarcinoma (P = 0.01)." (PMID 31533728, 2019). "In Asian populations, all previous studies, together with our own work, have shown that this germline APOBEC3A/B deletion increased breast cancer risk." (PMID 31533728, 2019). "Our results indicate that the expression level of uc011aoc derived from germline APOBEC3A/B deletion plays a tissue-specific functional influence on APOBEC-mutational signature in breast cancer." (PMID 31533728, 2019). "Surprisingly, the expression level of uc011aoc (APOBEC3A/B) was positively associated with the APOBEC-mutational signature only in breast cancer (P = 5.0 × 10− 10)." (PMID 31533728, 2019). "A common germline deletion covering the last intronic of APOBEC3A to the last exon of APOBEC3B (called APOBEC3A/B) is found to increase APOBEC-mutational signature in breast cancer, as a similar pattern driven by the elevated APOBEC3A or APOBEC3B expressions." (PMID 31533728, 2019). "The mutation data obtained in yeast reveal APOBEC3B and APOBEC3A as the only deaminases characterized whose target specificity matches the breast cancer kataegic mutations, strongly suggesting involvement of these deaminases in cancer kataegis." (PMID 24748981, 2014). "The mutation data obtained in yeast reveal APOBEC3B and APOBEC3A as the only deaminases characterised whose target specificity matches the breast cancer kataegic mutations, arguing very strongly for an involvement of these deaminases in cancer kataegis." (PMID 23599896, 2013). "It has been reported that APOBEC3H haplotype I (APOBEC3H-I) may majorly contribute to APOBEC-mutational signature for samples carrying germline APOBEC3A/B deletions in breast cancer." (PMID 31533728, 2019). "Similarly, our results revealed that germline APOBEC3A/B deletion was significantly associated with increased APOBEC-mutational signature only in breast cancer (P = 2.8 × 10− 6)." (PMID 31533728, 2019).
breast cancer (continued). "We found that expression level of the isoform uc011aoc transcribed from the APOBEC3A/B chimera was associated with a greater burden of APOBEC-mutational signature only in breast cancer, while germline APOBEC3A/B deletion led to an increased expression level of uc011aoc in multiple cancer types." (PMID 31533728, 2019). "Consistent with the observation of APOBEC-mutational signature, our results showed that germline APOBEC3A/B deletion was significantly associated with increased neoantigen loads only in breast cancer (P = 6.5 × 10− 3), while an opposite trend was observed in many other cancer types." (PMID 31533728, 2019). "However the peculiar clustering of same strand mutations at TpC dinucleotides observed in kataegic mutations in breast cancers constitutes a hallmark of the APOBEC3A and 3B deaminases that can be experimentally induced." (PMID 25237741, 2014). "The same study also demonstrated through comparison of mutation spectra that APOBEC3B and/or APOBEC3A were most likely responsible for the breast cancer hypermutation patterns, but allowed the possibility that other APOBEC3s might also contribute to genome mutation." (PMID 26861772, 2016). "High APOBEC3B expression was also associated with more APOBEC3-induced mutations in lung cancer, while both APOBEC3A and APOBEC3B levels were correlated with APOBEC3-induced mutations in breast cancer." (PMID 36978147, 2023). "Breast cancer samples with higher APOBEC3A expression had significantly more APOBEC-driven SGMs compared to cancers with lower expression (P = 1.3 × 10−6, Wilcoxon test) while weaker or subsignificant associations were seen with APOBEC3B expression." (PMID 37922356, 2023). "In breast cancers, APOBEC3A (A3A) and A3B showed positive correlations between their expression levels and the APOBEC mutation signature." (PMID 32176735, 2020). "We further showed that germline APOBEC3A/B deletion influences APOBEC-mutational signature, neoantigen loads and the relative abundance of T cell (CD8+) composition, but only in breast cancer." (PMID 31533728, 2019). "We observed ρ between − 0.118 and − 0.049, padj > 0.94 (n = 43, Ntests = 26,110) for correlations of both APOBEC3B and APOBEC3A expression levels with log(IC50) of tamoxifen in breast cancer cell lines." (PMID 29642934, 2018). "Also copy number variations affecting the APOBEC3 gene cluster on chromosome 22 might be important in breast cancer, since a germline copy number polymorphism, in which the gene-coding region of APOBEC3B is deleted and its 3′ UTR joined to APOBEC3A, associates with elevated risk of breast cancer." (PMID 26097867, 2015). "Decreased expression of “APOBEC3A” (OR 0.85; 95% CI 0.80–0.89; P = 1.51 × 10−9) and “NEK10” gene (OR 0.21; 95% CI 0.11–0.40; P = 1.69 × 10−6) were observed to be associated with the lower risk of breast cancer." (PMID 38659038, 2024). "Analysis of ATAC-seq data in multiple breast cancer cell lines identified two transcription factor sites in the APOBEC3A promoter region that could promote A3A transcription." (PMID 38805570, 2024). "In breast cancer, studies have detected enrichment of APOBEC3A, APOBEC3B, and APOBEC3H." (PMID 36978147, 2023). "Elevated APOBEC3A (A3A) levels result in APOBEC signature mutations; however, mechanisms regulating A3A abundance in breast cancer are unknown." (PMID 38155930, 2023). "In addition, the germline APOBEC3B deletion of ~30 kb, which extends between the last exon of APOBEC3A and the eighth exon of APOBEC3B and removes the entire APOBEC3B protein-coding region, was associated with increased breast cancer risk in Asian populations." (PMID 37510234, 2023). "A previous study showed that germline APOBEC3A/B deletion is associated with increased APOBEC-mutational signature in breast cancer, while a similar pattern, but without statistical significance, was observed in many other cancer types, such as bladder." (PMID 31533728, 2019).
breast cancer (continued). "Notably, our additional analysis showed the positive expression correlation between the isoform uc011aoc and APOBEC3A across a major of cancer types, especially in breast cancer." (PMID 31533728, 2019). "Interestingly, breast cancer cell lines were among the cancer types with positive correlation between APOBEC3A and APOBEC3B expression." (PMID 29642934, 2018). "Interestingly, the isoforms of the apolipoprotein B mRNA-editing enzyme catalytic polypeptide-like (APOBEC3A, APOBEC3B and APOBEC3H), implicated in breast cancer carcinogenesis, were also up-regulated." (PMID 25961742, 2015). "Although kataegis could easily have resulted from a transient spike in deaminase expression during tumour development, it was interesting to ascertain whether APOBEC3A or APOBEC3B expression could be detected or induced in breast cancer-derived cells." (PMID 23599896, 2013). "Moreover, they showed that APOBEC3B was highly expressed in breast cancer cell lines, and that APOBEC3B and APOBEC3A can also cause DNA damage in human cells." (PMID 23599896, 2013). "For APOBEC3A, the top ten pathways included those involved in epidermal and keratinocyte development and differentiation, whereas, consistent with observations in bulk RNA-seq data from breast cancer, all processes in the top ten for APOBEC3B were associated with mitosis (Dataset EV1)." (PMID 39548236, 2025). "Our study showed that the isoforms uc003awn (APOBEC3A) and uc003awo (APOBEC3B) were independently associated with a higher burden of APOBEC-mutational signature in multiple cancer types, while such an association for the uc011aoc (APOBEC3A/B) was only observed in breast cancer." (PMID 31533728, 2019). "Using univariate analysis to evaluate the overall effects of germline APOBEC3A/B deletion on APOBEC-mutational signature, we found that the deletion was significantly associated with increased APOBEC-mutational signature only in breast cancer (P = 5.6 × 10− 3)." (PMID 31533728, 2019). "However, still little is known regarding the role of APOBEC3A in breast cancer." (PMID 27552096, 2016). "Thus, APOBEC3B and/or APOBEC3A are the deaminases likely responsible for the breast cancer hypermutation although it remains possible that other APOBEC3s might contribute to genome mutation in other tumours." (PMID 23599896, 2013). "APOBEC3A and APOBEC3B expression can be induced by interferons, but this has been reported to be limited in urothelial cancer cell lines as compared to breast cancer lines." (PMID 35194151, 2022). "The similarity of yeast and breast cancer kataegis as well as increased APOBEC3B and APOBEC3A expressions in breast cancer samples are highly suggestive for the role of APOBEC3B and/or APOBEC3A in the breast cancer hypermutation." (PMID 36405752, 2022). "For example, rs12628403 on the intron of APOBEC3A alone explained 6.5% of FRR (OR = 1.49), compared with OR = 1.17 for overall breast cancers." (PMID 30323354, 2018). "Possible molecular impact of coordinated expression levels of APOBEC3A and APOBEC3B in the breast cancer cell lines analyzed in our study is of interest and requires further investigation." (PMID 29642934, 2018). "We examined APOBEC3A, APOBEC3B and APOBEC3G mRNA expression levels in a panel of 15 breast cancer cell lines (five luminal, five basal and five HER2+) by quantitative PCR." (PMID 27634334, 2016). "In addition, except the APOBEC3H gene, we found high DNA methylation levels of the remaining APOBEC members, including APOBEC1, APOBEC2, APOBEC3A, APOBEC4, and AICDA, in both HMEC and ER− breast cancer cells." (PMID 26682542, 2015). "Consistent with studies in other cell-types, the expression of APOBEC3A and APOBEC3B in some of the breast cancer cell-lines could be enhanced by treatment with phorbol ester or interferon alpha." (PMID 23599896, 2013).
breast cancer (continued). "APOBEC3A expression was not initially detectable in breast cancer cell lines, and APOBEC3B expression correlates strongly with overall mutations in multiple malignancies, leading many to initially believe that APOBEC3B is responsible for the majority of the APOBEC mutational signature." (PMID 29435122, 2018). "For other APOBEC family members, they show either extremely low (median log2-transformed RPKM < 0) mRNA levels (including APOBEC3A, APOBEC3H, APOBEC1, APOBEC2, APOBEC4, and AICDA), or no obvious expression differences between ER+ and ER− breast cancers (including APOBEC3D, APOBEC3F, and APOBEC3G)." (PMID 26682542, 2015).
viral infection (15 papers, 2016 to 2025). "While in viral infection the role of APOBEC3A is based on the innate immune response and mutations in the viral genome that inhibits their replication, in cancers, APOBEC is the cause of their mutations, the heterogeneity and diversity of tumours, and drug resistance." (PMID 38067256, 2023). "APOBEC3A plays an important role in the innate immune response to viral infection by editing the viral genome." (PMID 38021159, 2023). "The Western blot signal intensities were calculated from 3 independent replicates, and they confirmed the significant upregulation of Apobec3A at 48 h post wt infection, in comparison to the mock, as well as 72 hpi, in comparison to the minus virus infections." (PMID 37154747, 2023). "C60 nanofilm also downregulated cytidine deaminase apolipoprotein (APOBEC3A, or A3A), whose main function is the deamination of cytosine to uracil during mutagenesis and viral infections." (PMID 38067256, 2023). "Here the authors reveal that transient up-regulation of APOBEC3A and other pro-inflammatory genes can occur due to viral infection and genotoxic stress via multiple pathways." (PMID 34389714, 2021). "In this study, we find that both viral infection and genotoxic stress transiently up-regulate APOBEC3A and pro-inflammatory genes using two distinct mechanisms." (PMID 34389714, 2021). "For antiviral defense, endogenous Apobec3A can translocate to the nucleus during viral infection." (PMID 37154747, 2023). "APOBEC3A is an antiviral DNA deaminase often induced by virus infection." (PMID 37474103, 2023). "Low pre-treatment levels of APOBEC3A have been reported previously, and expression of both APOBEC3B and APOBEC3A has been reported to increase in response to cancer cell treatment with DNA-damaging agents or as part of cellular interferon-induced transcriptional response to viral infections." (PMID 29642934, 2018). "This dataset included some genes with known antiviral functions, such as APOBEC3A and OASL, which is potentially relevant for the inability of patients with high endogenous ISG levels to spontaneously clear the viral infection." (PMID 28360091, 2017). "We observed that Apobec3A was SUMOylated, even in the absence of HAdV, which was increased after viral infection to a certain extent, although this result was not statistically significant under our experimental setup." (PMID 37154747, 2023). "In a previous EPF genome-wide expression study (GWES), several genes involved in the early stages of viral infection were overexpressed in patients with the generalized form of EPF compared to healthy individuals, including IFITM3, APOBEC3A, APOBEC3G, OAS1, OASL, SERINC3, and RPLP2." (PMID 35632621, 2022).